MLN (motilin)
Diseases named in the same sentence as MLN in open-access papers (continued):
Sharing a sentence is not in itself a finding about the gene and the disease.
gastric ulcer (1 paper, 2025). An ulcerated lesion in the mucosal surface of the stomach. "This study investigated the effects of probiotics combined with quadruple therapy on serum levels of tumour necrosis factor-a (TNF-a), interleukin-6 (IL-6), C-reactive protein (CRP), gastrin (GAS), and motilin (MTL) in patients with Helicobacter pylori (Hp)-positive gastric ulcer (GU)." (PMID 41281280, 2025). "This study aimed to explore the clinical efficacy of probiotics plus quadruple therapy on Serum levels of tumour necrosis factor-a (TNF-a), interleukin-6 (IL-6), C-reactive protein (CRP), gastrin (GAS) and motilin (MTL) in treating Helicobacter pylori (Hp)-positive gastric ulcer (GU)." (PMID 41281280, 2025).
Headache (1 paper, 2012). Cephalgia, or pain sensed in various parts of the head, not confined to the area of distribution of any nerve. "In the evening, plasma motilin correlated also with headaches (r = 0.41, p = 0.006), but not with the AMS sum score." (PMID 22970220, 2012).
hypereosinophilic syndrome (1 paper, 2022). Hypereosinophilic syndrome (HES) constitutes a rare and heterogeneous group of disorders, defined as persistent and marked blood eosinophilia and/or tissue eosinophilia associated with a wide range of clinical manifestations reflecting eosinophil-induced tissue/organ damage. "Whereas the pathogenesis of idiopathic hypereosinophilia and the hypereosinophilic syndrome remain widely unclear, in the case of CEL-NOS and MLN-Eo defects on the level of the myeloid progenitor cell are disease defining." (PMID 34654952, 2022).
Hypertension (1 paper, 2018). The presence of chronic increased pressure in the systemic arterial system. "It is known that erythromycin stimulates motilin release which may induce AP by causing spasms of the sphincter of Oddi, leading to an abrupt of hypertension in the pancreatic duct and pancreatitis." (PMID 29720098, 2018).
hyperthyroidism (1 paper, 2021). Overactivity of the thyroid gland resulting in overproduction of thyroid hormone and increased metabolic rate. "On the other hand, a study on patients with hyperthyroidism found lower levels of plasma motilin compared with the controls, as well as a negative correlation between thyroxine (T4) and the motilin levels." (PMID 34575041, 2021).
hypothyroidism (1 paper, 2021). Abnormally low levels of thyroid hormone. "There are no studies on the motilin levels in human subjects with hypothyroidism." (PMID 34575041, 2021).
influenza (1 paper, 2021). An acute viral infection of the respiratory tract, occurring in isolated cases, in epidemics, or in pandemics; it is caused by serologically different strains of viruses (influenzaviruses) designated A, B, and C, has a 3-day incubation period, and usually lasts for 3 to 10 days. "Finally, co-housing decreased lung CD8+ T cell differences between influenza-infected WT and Lcn2-/- mice, while mLN size was unaffected." (PMID 33905460, 2021).
insomnia (1 paper, 2020). A sleep disorder characterized by difficulty in falling asleep and/or remaining asleep. "Insomnia and sleep deprivation can cause increased production of gastrin, regulating gastric acid secretion and motilin (MTL) that activate pepsin." (PMID 32617111, 2020).
lymphoma (1 paper, 2024). A malignant (clonal) proliferation of B- lymphocytes or T- lymphocytes which involves the lymph nodes, bone marrow and/or extranodal sites. "These insights help to explain the mLN tropism common to some aggressive lymphomas and offer clues to potential therapeutic vulnerabilities in these malignancies." (PMID 39025963, 2024).
mixed phenotype acute leukemia (1 paper, 2026). An acute leukemia of ambiguous lineage. "In addition to MLN-eo-TK, JAK2 rearrangements can also be found in BCR::ABL1-negative myeloproliferative neoplasms (MPN), myelodysplastic neoplasms (MDS), MDS/MPN overlap syndromes, B/T lymphomas, acute myeloid (AML), lymphoblastic (ALL) or mixed- phenotype acute leukemia (MPAL)." (PMID 41530508, 2026).
Peptic ulcer (1 paper, 2024). The term peptic ulcer refers to acid peptic injury of the digestive tract, resulting in mucosal break reaching the submucosa. "The SGLT2I dapagliflozin may decrease risk of peptic ulcer by lowering blood glucose and modulating ghrelin, motilin, and gastrin levels, thereby decreasing gastric acidity and inflammation while promoting mucosal healing." (PMID 38856768, 2024).
peritonitis (1 paper, 2023). Inflammation of the peritoneum (tissue that lines the abdominal wall and covers most of the organs in the abdomen). "Peritonitis from anastomotic leakages, ischemia of the pyloric muscle cells, damage to the vagal nerve, and reduced circulating motilin levels are discussed." (PMID 36902534, 2023).
prostate carcinoma (1 paper, 2022). A carcinoma that arises from epithelial cells of the prostate gland. "A recent study suggested that MLN could also suppress prostate cancer (PCa) cells specifically by shutting down the transcription of the androgen receptor (AR) and its downstream targets." (PMID 35354476, 2022). "These drugs may serve as potential candidates for combination therapy with MLN in prostate cancer." (PMID 35354476, 2022).
sarcopenia (1 paper, 2024). Progressive decline in muscle mass due to aging which results in decreased functional capacity of muscles. "It has previously been shown that two SNPs (MLN rs12055409 and GBF1 rs2273555) associated with higher levels of muscle mass and strength in elite Russian weightlifters protect against sarcopenia." (PMID 39056794, 2024).
Stroke (1 paper, 2022). Sudden impairment of blood flow to a part of the brain due to occlusion or rupture of an artery to the brain. "In cases of PHS stroke patients, the plasma motilin (MTL) level was obviously increased compared with the other syndrome types, which could further elucidate that stroke patients of PHS were more likely to suffer from the slowing of gastric emptying to release more MTL via neurosecretory feedback." (PMID 36327217, 2022).
infection (6 papers, 2018 to 2024). The state of being infected such as from the introduction of a foreign agent such as serum, vaccine, antigenic substance or organism. "SJL mice, similar to BALB/c mice, displayed limited IFN-γ availability in mLN, spleen and siLP, poor small intestinal Th2/1 accumulation at early stage of infection and stronger M2 polarization in the peritoneal cavity compared to susceptible C57BL/6 mice." (PMID 35690651, 2022). "Interestingly, primary infection with Hpb resulted in a similar worm count in the intestines of RelBΔDC and control mice but RelBΔDC mice exhibited a reduced mLN cellularity and a significantly higher parasite burden after secondary Hpb infection." (PMID 39443450, 2024). "The data presented in this article indicate that mLN Trms also have an enhanced functional avidity that could allow them to exhibit this viral control in response to lower levels of Ag presented at early stages of infection." (PMID 36220187, 2022). "Thus, we identified whether populations of CD4+ T cells and Foxp3+ Tregs within the TC and mLN altered upon infection according to the applied gating strategy (Online Resource 4)." (PMID 29931394, 2018). "rIL-7 treatment led to an increase in cellularity and recovery of T and B the iLN while the mLN did not expand further in H. polygyrus-infected mice, supporting the notion that the size of the lymphocyte pool may be a limiting factor in determining LN size both during steady state and infection." (PMID 29772005, 2018).
tumor (4 papers, 2020 to 2025). "mLN involvement was observed in 25 of 27 tumor-bearing Gα13-deficient mice; in 12 mice, tumors were present in mLNs only." (PMID 39025963, 2024). "Previous studies have shown that RhoA activity could contribute to the therapeutic effects of MLN by blocking tumor-associated angiogenesis." (PMID 35354476, 2022). "In androgen-independent PC3 cells, MLN was shown to promote cell proliferation and tumor sphere formation and to accelerate cancer cell migration." (PMID 35354476, 2022). "The current understanding is that similar to clinically approved proteasome inhibitors, MLN exerts its anticancer activity by stabilizing a number of tumor suppressors and blocking several oncogenic pathways." (PMID 35354476, 2022). "The tumor-bearing mice have enlarged spleen, mLN and pLN, and B cell expansion in the lung, liver, and kidney, and also significantly shorter lifespan." (PMID 32695674, 2020).
cancer (2 papers, 2021 to 2025). A tumor composed of atypical neoplastic, often pleomorphic cells that invade other tissues. "Therefore, the neural pathway involved in motilin-induced gastric contraction is partially involved in anti-cancer drug induced vomiting mechanisms." (PMID 34497583, 2021). "Similar to motilin-induced contraction, 5-HT, the 5-HT3 receptor and afferent terminals of the vagus nerves have been shown to be involved in the vomiting caused by the anti-cancer drug cisplatin." (PMID 34497583, 2021).
gastrointestinal disease (1 paper, 2024). A disease that occurs in the gastrointestinal system, excluding the hepatobiliary system. "This LC-MS/MS method can be used as a baseline for further clinical studies into motilin physiology in human volunteers in human health and different gastrointestinal disease states, and can be readily multiplexed within the same assay for measurement of other hormones." (PMID 38544692, 2024).
MLN also shares sentences with these, for which no sentence is quoted: lymphoid neoplasm (3 papers); acute leukemia (1); acute myeloid leukemia (1); carcinoid tumor (1); Chagas disease (1); chronic atrophic gastritis (1); food allergy (1); gastrointestinal tumors (1); Hyperinsulinemia (1); ileus (1); ischemia (1); leukemia (1); lung disease (1); lymphopenia (1); myelodysplastic neoplasms (1); myeloproliferative neoplasm (1); non-alcoholic fatty liver disease (1); pancreatitis (1); pneumonia (1); postpartum hemorrhage (1); steatosis (1); thyroid disorders (1); type 2 diabetes mellitus (1).